Y_RNA (Y RNA )
Gene: Miscellaneous RNA gene on chromosome 9 (112,169,286 to 112,169,397, forward strand). Ensembl gene ENSG00000200261.
Homologues: Orthologues: chimpanzee Y_RNA (100% identical), macaque Y_RNA (89% identical). Paralogues in human: RNY1P5 (88% identical), Y_RNA (87% identical), Y_RNA (86% identical), Y_RNA (85% identical), Y_RNA (84% identical), RNY1P1 (83% identical), Y_RNA (83% identical), Y_RNA (82% identical), RNY1 (81% identical), Y_RNA (81% identical), RNY1P11 (80% identical), Y_RNA (80% identical), and 96 more.